CD40 (CD40 molecule)
Diseases named in the same sentence as CD40 in open-access papers (continued):
Sharing a sentence is not in itself a finding about the gene and the disease.
tumor (continued). "Within tumor tissue, CD40 triggering by both CD40L+ lymphocytes and sCD40L may directly activate signalling pathways contributing to the transformed phenotype of UNPC cells, particularly in the LMP-1-negative cases." (PMID 17331231, 2007). "Our CD40-targeted approach of Ad transduction results both in the upregulation of costimulatory and adhesion molecules and in the release of IL-12, thus meeting the requirements for tumor-specific CTL activation." (PMID 14520439, 2003). "The discrepancies in CD40 expression between NB cell lines and fresh tumour cells may be related to the presence of in vivo factors (e.g. IFN-γ) capable of upregulating surface CD40 in the tumour microenvironment." (PMID 12771917, 2003). "CD40 is expressed on APCs and has also been reported on subsets of PDAC tumor cells, cancer-associated fibroblasts, and endothelial cells, indicating that CD40 agonists may affect immune activation, stromal/vascular remodeling, and context-dependent tumor-cell-intrinsic signaling." (PMID 42279326, 2026). "Interaction of sotigalimab with CD40 triggers the cellular proliferation and activation of APCs, including B lymphocytes, dendritic cells, macrophages, and monocytes, leading to the generation of both T cell–dependent as well as humoral immune responses against tumor cells." (PMID 39907035, 2025). "This suggests that agonistic CD40 antibody therapy not only remodels the tumor microenvironment by promoting pro-inflammatory and antitumor immune responses but also effectively suppresses oncogenic signaling, ultimately inhibiting tumor progression and improving survival outcomes." (PMID 40060615, 2025). "Of those, clusters 10 and 8 mapped to the lower and higher “activation bridges” on the UMAP space, respectively, and expressed higher level of Cd274 and Cd40, suggesting that they might represent endpoint activated cDC1 states in tumours, while clusters 7 and 9 may correspond to transitional states." (PMID 40745918, 2025). "Additionally, correlations between CD68 expression and six TIICs (B cells, CD4+ T cells, CD8+ T cells, macrophages, NK cells, and cancer-associated fibroblasts) or four common TICs (PDCD1, CTLA4, IDO1, and CD40) were assessed using the Tumor Immune Estimation Resource (TIMER)." (PMID 40918116, 2025). "Similarly, in subcutaneous PDAC models, mice treated with anti-IL-1R1 antibodies showed accelerated tumor growth compared with the untreated group, and treatment with the combination of anti-IL-1R1 and agonistic CD40 antibodies performed worse than agonistic CD40 antibody monotherapy." (PMID 40060615, 2025). "Similarly, the activation of the CD40 signal also leads to the activation of enhancers at pro-inflammatory gene loci in TAMs through metabolic reprogramming, thereby coordinating the polarization of the anti-tumor phenotype." (PMID 40032852, 2025). "Furthermore, we demonstrated that the significant association between the high expression of CD40 and the T-cell costimulatory molecules CD28 or GITR was most pronounced within the context of an "immunologically hot" tumor microenvironment, defined here by high CD4/CD8 RNA expression." (PMID 41182434, 2025). "Our data suggest a decrease in exo-CD40 expression could indicate tumor progression in PDAC." (PMID 40003965, 2025). "Similarly, administration of oncolytic adenovirus coexpressing OX40 and CD40 ligands resulted in synergistic activation of OX40 and CD40, induction of tumor-specific CD8+ effector T cells, and improved control of melanoma growth in tumor peptide-vaccinated mice." (PMID 40178907, 2025). "We also consider it possible that B7‐H3 could, like CD40, recruit other membrane microdomains or adhesion molecules to form membrane raft complex after combining with c‐Met and to initiate tyrosine phosphorylation of intracellular substrates in tumor cells." (PMID 40859957, 2025).
tumor (continued). "The study of the tumor myeloid compartment showed, that while the number of microglia increased with the anti-CD40, the levels of macrophages and monocytes were significantly higher with the virus and the combination compared to IgG control- or anti-CD40-treated groups." (PMID 40578365, 2025). "Hence, targeting the CD40 pathway of CD40+ tumour cells may increase the immune‐mediated killing via TRAIL receptors." (PMID 38494863, 2024). "Among them, the immune checkpoint CD40L binding to CD40 could increase the immunomodulatory ability of DCs, induce effector cell proliferation and enhance immunotoxicity to tumor cells, which further indicated that CDN2 and CDN4 had strong immune activation ability." (PMID 38461356, 2024). "Furthermore, CD40L signalling in CD40 positive tumour cells can lead to induction of apoptosis." (PMID 38494863, 2024). "Agonists to CD40 (CD40a) can trigger pro-inflammatory cytokine secretion and promote maturation and activation of macrophages and other antigen presenting cells to enhance anti-tumor activity, stimulate antigen presentation to T cells and promote influx of cytotoxic T cells." (PMID 38533720, 2024). "Finally, the authors found that alloIgG isolated from healthy donors could similarly induce TADC activation in the presence of tumor necrosis factor alpha (TNF-α) and CD40 when cultured with tumor cells, validating the clinical performance of this approach." (PMID 38461238, 2024). "Thus, we sought to determine whether adding anti-CD40 treatment further improved tumor immunity against B16-F10DNA-PK–KO tumors." (PMID 39436696, 2024). "While CD40 agonism broadly activates a variety of hematopoietic cell types that include B cells and macrophages, its activation of DCs, in particular cDC1s, plays an essential role in tumor immunity as illustrated by abrogation of tumor control in murine Batf3-/- models." (PMID 38903502, 2024). "Moreover, the gadolinium-coated PDA nanobowls demonstrate the capacity for loading immunotherapy drugs (Anti-CD40) with activated release in acidic pH levels characteristic of the tumor microenvironment, with enhanced release following administration of radiation therapy in vitro." (PMID 39598603, 2024). "Also, vaccination studies using CD40-activated B cells acting as APCs could activate and expand anti-tumour naive and memory T cells." (PMID 39199652, 2024). "Interestingly, we observed an increase in tumor clearance compared to the lower doses tested earlier, which could be due to a combination of induction of effective T cell responses and CD40-induced Th1 remodeling in lymph nodes and tumor compartments." (PMID 39500897, 2024). "Interestingly, tumor shrinkage was mediated by CD40-activated TAMs." (PMID 37895882, 2023). "Furthermore, previous studies have shown that CD40 stimulation could induce strong systemic anti-tumor responses leading to regression of tumors in preclinical models, and it has also been shown to synergize with CBT." (PMID 37548358, 2023). "Furthermore, treatment of tumor-bearing mice with PPARδ inhibitor could efficiently diminish the number and function of IL-10+ Bregs, and act synergistically with anti-CD40 or anti-PD1 antibody to improve antitumor immune responses." (PMID 37291146, 2023). "The interaction between CD40 and its ligand CD40L can cause tumor growth inhibition due to immunologic mechanisms and apoptosis induction; alternatively, it may promote tumor growth through the action of cytokines and growth factors, such as interleukin 6 and vascular endothelial growth factor." (PMID 37970926, 2023). "For instance, CD40 could enhance the phagocytic activity of macrophages recovered by CD47‐SIRPα blockade, and a fusion protein with high affinity to bind CD40 and CD47 performed better than either CD47 blockade or CD40 agonist alone in a mouse CT26 tumor model." (PMID 37706196, 2023).
tumor (continued). "Therefore, we stained tumor sections for Cxcl9 and Cxcl10 from untreated KPC2a-bearing mice and mice treated with αPD-L1 or CD40 agonist as such therapies may enhance IFNγ, which induces Cxcl9/Cxcl10." (PMID 36472588, 2023). "Fusion proteins such as Fas-CD40 may enhance anti-tumor activity when co-expressed with CARs." (PMID 37200859, 2023). "Considering that CD40-targeting agents are often accompanied by dose-limiting toxicities, this quantitative assessment of CD40 expression by tumor cells may help guide selection of patients and tumor types that would be more likely to benefit from these drugs." (PMID 36894898, 2023). "While these therapies aim to target CD40 molecules expressed on APCs, previous studies have reported the presence of CD40 on a variety of other cell types, including macrophages, monocytes, platelets, fibroblasts, epithelial cells, endothelial cells, and most importantly tumor cells." (PMID 36894898, 2023). "The CD40 molecule, the cell surface co-stimulatory member of the TNF superfamily on DCs, is associated with maturation, activation of a specific phenotype necessary for effector T cell activation, as well as DC survival and an anti-tumour DC40-dependent response." (PMID 36980527, 2023). "However, it may be worth further examining CD40 expression by tumor cells, as it could affect the efficacy of drugs targeting CD40." (PMID 36894898, 2023). "Moreover, Linde and colleagues discovered that combined therapies of CD40 agonist, tumour necrosis factor and tumour‐binding antibodies induced activation of neutrophils via C5a, which subsequently mediated oxidative damage and facilitated T cell‐independent cancer cell clearance." (PMID 37491740, 2023). "Therefore, future investigations should address whether preconditioning the tumor metabolic milieu with treatments favoring metabolic reprogramming, such as those identified in our study, can potentiate agonistic anti-CD40-mediated antitumor responses." (PMID 36823405, 2023). "Furthermore, engagement with agonistic anti-CD40 antibody may stimulate IL-10+ Bregs, leading to an increase in number and function in tumor-bearing mice by a mechanism largely dependent on PPARδ." (PMID 37291146, 2023). "Thus, recovery of CD40 using appropriate stimulators can promote anti‐tumor immunity." (PMID 35301813, 2022). "The observation that CD40 signaling in APCs may remodel the TME and that effective T cell therapy results in T cell-directed and CD40-mediated remodeling of the tumor stroma, suggests that this approach has potential to alter the contours of the tumor immune environment." (PMID 35937775, 2022). "Therefore, administration of a CD40 agonist several days after chemotherapy or radiotherapy may amplify the tumor antigen-induced immune responses." (PMID 35139879, 2022). "Besides, CD40 is widely expressed by various tumor types including CRC." (PMID 35715855, 2022). "Many cells in the tumor microenvironment, including stromal cells and the infiltrating immune cells, express CD40 and 4-1BB; thus, expression of complementary activating ligands via LOAd703 could activate many types of cells in the tumor milieu to induce antitumor immune response." (PMID 36091031, 2022). "Thus, the maximal exploitation of potent autonomous CD40 agonists for tumor therapy may require defined treatment regimens that restrict the antibody activity to the tumor area and/or systemically inhibit CD40 effector molecules." (PMID 36361658, 2022). "We showed that DMXAA improved antigen presentation, yet CTL function was compromised, therefore we hypothesized that combining DMXAA with an agonist anti-CD40 antibody that activates DCs or with IL-2 that expands tumor-specific T cells might improve DMXAA efficacy." (PMID 36466911, 2022). "Therefore, we proposed that malignant T cells activated B cells in TCM patients via a CD40L/CD40 axis, and highly infiltrated B cells may promote tumor progression by activating Tregs." (PMID 35241665, 2022).
tumor (continued). "Moreover, the suppressive effect of CD40 agonist/IL15 could still be observed in re-challenge experiments after a 100-day tumor-free period." (PMID 35453676, 2022). "Agonistic CD40 monoclonal antibodies have been under active investigation as novel immunomodulatory agents that could potentially overcome tumor signals that weaken DCs, leading to enhanced antigen-dependent DC activity and a break in tumor immune tolerance." (PMID 36077755, 2022). "CD40L and CD30L expressed by eosinophils are functionally active and able to transduce proliferative signals on CD40+ and CD30+ HRS cells, suggesting that they may contribute, likely together with other cell types, to CD30 and CD40 activation of tumor cells in cHL lymph nodes." (PMID 35626032, 2022). "Importantly for translation, we also showed that tumor debulking could be synergistic with immunotherapies delivered as immune-gene therapy, via activating anti-CD40 or by using neoantigen-based vaccination therapy." (PMID 35431929, 2022). "However, if CD40 stimulation is used to remodel the tumor microenvironment to allow more chemotherapy access, then sequencing CD40 prior to chemotherapy may be logical." (PMID 34282297, 2022). "In addition, in a recent study, macrophage depletion using the F4/80 antibody in elderly mice improved the IL-2/anti-CD40 treatment response and achieved up to 78% tumor regression compared to 38% tumor regression in the intact macrophages control and reduced age-related treatment-induced cachexia." (PMID 36679900, 2022). "Our work shows that hypoxia enhances IL-6-mediated CD40 expression in tumor Mφs, implicating that cancer therapy by modulation of tumor metabolism or normalization of blood vessels to relieve tumor hypoxia may need additional CD40 agonist treatment to stimulate anti-tumor immunity." (PMID 34103524, 2021). "Additionally, M2-like TAMs activated using CD40 agonists can reportedly reacquire antigen-presenting capabilities and become tumoricidal, resulting in the reestablishment of tumor immune surveillance and the short-term reduction of tumor volume." (PMID 34603327, 2021). "However, we clearly cannot rule out the possibility that CD40 upregulation itself is the key event associated with the RGS-initiated suppression of tumor growth." (PMID 34092233, 2021). "Therefore, we first analyzed the levels of CD40 expression on all tumor cell lines." (PMID 33180184, 2021). "In general, the effect of CD40 on tumorigenesis and response to therapy (sensitivity and toxicity) may largely depend on the context of the tumor type and cancer stage, cytokine availability, ligand/receptor distribution, and crosstalk among different stimuli, cell types, and signaling pathways." (PMID 34758832, 2021). "However, systemic CD40 activation can also induce tumor regression via mechanisms not dependent on T cells, such as activation of tumoricidal macrophages and polarization of tumor-infiltrating myeloid cells, which sensitize PDA to chemotherapy." (PMID 33497362, 2021). "Meanwhile, the percentage of CD11c+, CD40+, CD80+, and CD86+ DCs significantly increased in the mCALR group, while no significant change was observed in the percentage of MHCII+ DCs, suggesting that mCALR expression was closely associated with DC infiltration in tumor tissues." (PMID 34660305, 2021). "Comparing with controls, CD40 activation groups could obviously suppress TC-1 tumor growth." (PMID 32536922, 2020). "Furthermore, while FcR binding of tumor-immune complexes has been suggested to promote tumor progression, we have found that combining tumor-binding antibodies with DC adjuvants and CD40 agonists results in extremely potent anti-tumor responses in a manner that is FcR-dependent." (PMID 32657757, 2020).
tumor (continued). "Furthermore, the ability of mCD40L to also directly induce cell death in CD40-expressing carcinomas, subsequently releasing tumour-specific antigens into the tumour microenvironment highlights the potential for mCD40L as a multi-faceted anti-cancer immunotherapeutic." (PMID 31941968, 2020). "Since it had been demonstrated that the CD40 agonist also increases the expression of IL‐15Rα on DCs, we hypothesised that combining both agents may result in enhanced immune activation and increased anti‐tumor effects." (PMID 32821382, 2020). "CD40 agonists are reported to induce anti-tumoral cytotoxic activity by TAMs; several CD40-activating antibodies and recombinant ligands are currently under clinical trials for solid tumors as single agents or in combination with chemo- and immuno-therapy, or tumor vaccines." (PMID 32823961, 2020). "Since it has been demonstrated that CD40 agonists also increase the expression of IL‐15Rα on DCs, we hypothesised that combining both agents might result in enhanced immune activation and increased anti‐tumor effects." (PMID 32821382, 2020). "And recent studies demonstrate that it's possible to engineer a tumor-targeted CD40 molecule by conjugating a CD40 agonist mAb chemically with a tumor-homing peptide could potentially maximize antitumor potency while limiting systemic toxicity in clinical studies." (PMID 32536922, 2020). "We therefore tested multiple cytostatic drugs for their impact on tumor cell killing as well as in in vivo immunization model in which T cell priming requires antigen cross-presentation by activated DCs, using agonist anti-CD40 Abs as the dendritic cell (DC)-activating signal." (PMID 33024933, 2020). "Moreover, moDCs could be targeted by agonistic anti-CD40 antibody, supporting moDC differentiation, effector T-cell expansion and anti-tumor immunity." (PMID 32690667, 2020). "Stimulated CD40 could play a direct role in killing tumor cells." (PMID 31708918, 2019). "Since our results indicate that H-1299 tumor cells downregulate the expression of CD40, CD80, CD86, and HLA-DR on CD1c+ DCs isolated from healthy donors, we proposed that H-1299 cells may also block the expression of costimulatory molecules on CD1c+ DCs derived from NSCLC patients." (PMID 31921114, 2019). "Therefore, the relationship between the expression of CD40 and tumor growth may be related to tumor types." (PMID 31708918, 2019). "Anti-CD40 was combined with anti-CSF-1R to create a pro-inflammatory environment eliciting T-cell responses before depletion of TAMs or with chemotherapies such as imatinib (tyrosine kinase inhibitor) with strong tumor regression in a gastrointestinal tumor mouse model." (PMID 31547627, 2019). "Notably, combining CD40 agonists with TLR3 activation was shown to be sufficient to reverse the immunosuppressive phenotype of tumor-infiltrating DC into APCs capable of priming anti-tumor T cell responses." (PMID 31031762, 2019). "Furthermore, CD40 expression on tumor cells correlated with a longer overall survival (OS), suggesting that the interaction between tumor cells and CD40L+ CD4+ T cells could stimulate antigen presentation and lymphoma-specific T-cell responses." (PMID 31261914, 2019). "Importantly, however, it was suggested that RCC tumours could be targeted more effectively by combining CD40-mediated immune activation together with delivery of the CD40 signal to the tumour itself." (PMID 31815003, 2019). "Agonistic anti-CD40 mAb (which activates effector macrophages) and CpG-oligodeoxynucleotides (a toll-like receptor 9 agonist that acts as a danger signal) induce tumor destruction via innate effector cells, leading to increased presentation of tumor antigens and an adaptive T cell response." (PMID 31810498, 2019). "Furthermore, in vitro studies showed that elderly derived IL-2/anti-CD40-activated macrophages could restore age- and tumor-related T cell function." (PMID 30459812, 2018).